CPSF6 (cleavage and polyadenylation specific factor 6)
Diseases named in the same sentence as CPSF6 in open-access papers (continued):
Sharing a sentence is not in itself a finding about the gene and the disease.
viral infection (11 papers, 2017 to 2026). "All these data indicated that the global 3’ UTR shortening caused by CPSF6 deficiency orchestrates the cellular antiviral capacity to inhibit viral infection." (PMID 38416782, 2024). "Hence, the global 3’ UTR shortening caused by reduced CPSF6 during viral infection orchestrates the cellular antiviral capacity to inhibit viral infection." (PMID 38416782, 2024). "After statistical analysis, we found that more than 2000 genes showed shortened 3’ UTRs in CPSF6-deficient cells at rest and after viral infection, while the 3’ UTRs of approximately 1500 genes became longer when CPSF6 was ectopically expressed in CPSF6-deficient cells." (PMID 38416782, 2024). "In this study, we found that the expression of CPSF6 was significantly decreased after viral infection as well as bacterial and helminthic infection." (PMID 38416782, 2024). "In this study, after identifying the reduced expression of CPSF6, a subunit of the CFIm, during viral infection, we further showed that knocking down of CPSF6 promotes the activation of IFN-I signalling and inhibits viral replication." (PMID 38416782, 2024). "Not only viral infections, but also bacterial or helminthic infections can lead to downregulation of CPSF6." (PMID 38416782, 2024). "Here, we further identified that the protein expression of CPSF6 was significantly and universally reduced facing multiple viral infection, leading to the global usage of pPASs and the preferential generation of transcripts with short 3’ UTRs." (PMID 38416782, 2024). "We describe early post-nuclear entry steps in which viral infection enhances the phase separation of CPSF6, building HIV-1 MLOs." (PMID 36314049, 2023). "To examine the interaction of the viral capsids with CPSF6, we performed an infection-based assay using a truncated version of CPSF6 (CPSF6-358), which blocks viral infection through CA interactions." (PMID 31511380, 2019). "We aimed to investigate the role of the FG domain of CPSF6 in viral infection." (PMID 41493399, 2026). "Here we further found that, the reduced protein abundance of CPSF6, one of the core 3’ processing factors, promotes the usage of proximal poly(A) sites (pPASs) of many immune related genes in macrophages and fibroblasts upon viral infection." (PMID 38416782, 2024). "Consistent with our previous observation, the average 3’ UTR length in cells was decreased after viral infection and decreased even more upon CPSF6 deficiency, further demonstrating the priority usage of proximal PASs in the absence of CPSF6." (PMID 38416782, 2024). "All these data indicated that downregulated expression of CPSF6 is a common phenomenon in the immune response to infection, implying that CPSF6 may play an important regulatory role in pathogen infection, especially viral infection." (PMID 38416782, 2024). "Interestingly, the protein expression of CPSF6 was significantly decreased after viral infection or analogue simulation, accompanied by a decreased RNA abundance, while CPSF5 and CPSF7 (CFIm59) showed no significant changes." (PMID 38416782, 2024). "On the other hand, this phenomenon could also be prompted by the overexpression of CPSF6 due to the viral infection." (PMID 36314049, 2023). "We observed an increased amount of this protein upon viral infection, and this phenomenon could ensure a bimodal role of CPSF6, one for the biology of the host cell and the other for the viral replication." (PMID 36314049, 2023). "CPSF6 proteins have been shown to cluster in NSs upon viral infection." (PMID 36314049, 2023). "Thus, the expression of CPSF6 upon viral infection may be regulated by multidimensional mechanisms, further highlighting the functional importance and adjustability of CPSF6." (PMID 38416782, 2024).
viral infection (continued). "Furthermore, despite advances in understanding mRNA APA events in activated macrophages and recent discoveries regarding the role of CPSF6 during viral infections, substantial gaps exist in our knowledge of APA regulators such as Nudt21 in macrophage-mediated inflammatory diseases." (PMID 39537902, 2024). "Knockdown of CPSF5 (CFIm25) or CPSF6 (CFIm68), two key subunits of the CFIm tetramer leads to a widespread increase in the use of proximal PASs (pPASs), making this complex a key candidate to reveal the genome-wide landscape of shortened tandem 3’ UTRs upon viral infection." (PMID 38416782, 2024). "The formation of CPSF6 condensates is likely to be important for viral infection; therefore, we sought to determine whether the CPSF6 condensates are transient or stable structures since some viruses require the assembly and disassembly of condensates for the completion of their viral life cycle." (PMID 37414787, 2023). "To explore the mechanism of the widespread dynamic changes in APA in host cells after viral infection, we first tested the change in the mRNA expression of CPSF6 and the other two members of CFIm upon viral infection or nucleic acid analogue stimulation." (PMID 38416782, 2024). "Given the roles of CPSF6 in APA processing and in regulating viral infection we hypothesized that CPSF6 acts as an antiviral immune regulator by influencing APA and the 3’ UTR length." (PMID 38416782, 2024). "We found that more transcripts were profoundly upregulated (>3 fold, FDR-adjusted P<0.01, Fisher’s exact test) in Cpsf6-/- L929 cells than in WT cells with or without viral infection, while the ectopic expression of CPSF6 inhibited this upregulation." (PMID 38416782, 2024).
breast carcinoma (10 papers, 2019 to 2025). "Other altered genes in these patients are FRS2, LYZ, and CPSF6, all associated to breast cancer pathogenesis." (PMID 36860495, 2022). "HER2-overexpressing and triple-negative subtypes depend on CPSF6 for viability and tumorigenic capacity in aggressive breast cancer cells of luminal B, and CPSF6 is overexpressed in human breast cancer cases, which is associated with poor prognosis." (PMID 34217312, 2021). "The overexpression of CPSF6 is clinically identified in human breast cancer, moreover, its expression correlates with poor outcomes of patient." (PMID 36081995, 2022). "Studies have shown that CPSF6 promotes the development of colon cancer and CPSF6 and all core paraspeckles proteins have found to be highly expressed in human breast cancer, which is correlated with poor prognosis." (PMID 34217312, 2021). "In breast cancer, downregulation of CPSF6 leaded to the decrease of proliferation, migration and invasion of cells." (PMID 34217312, 2021). "They further suggest that CPSF6 serves as an oncogene in aggressive breast cancer." (PMID 36446361, 2022). "In additional, overexpression of CPSF6 shows prognostic value in breast cancer." (PMID 36446361, 2022). "CPSF6 is able to regulate A-to-I RNA editing process and tumorigenesis in breast cancer." (PMID 36446361, 2022). "Overexpression of CPSF6 predicts poor prognostic outcomes of breast cancer." (PMID 36446361, 2022). "CPSF6 has been recently reported to be of clinical relevance in breast cancer." (PMID 33648552, 2021). "Although CPSF6 played roles in aggressive breast cancer behavior and exhibited a novel CPSF6-RARG fusion variant in acute myeloid leukemia patients, the role of CPSF6 in GC is still unknown." (PMID 34594359, 2021). "Although several studies have demonstrated the involvement of CPSF6 in HIV infection and breast cancer, the role of CPSF6 in myeloid leukemia has not yet been clarified." (PMID 31709264, 2019).
gastric cancer (6 papers, 2008 to 2025). A primary or metastatic malignant neoplasm involving the stomach. "The aim of the present study was to characterize CPSF6 in human gastric cancer (GC)." (PMID 34594359, 2021). "To directly demonstrate the functional role of PGC genes in cellular invasion, we performed siRNA experiments where five PGC genes (p53CSV, MAP3K11, MTCH2, CPSF6, SKIP) were silenced in poorly-metastatic AGS gastric cancer cells." (PMID 18636107, 2008).
acute myeloid leukemia (3 papers, 2021 to 2022). Acute myeloid leukemia (AML) is a group of neoplasms arising from precursor cells committed to the myeloid cell-line differentiation. "Previous studies have shown that CPSF6 is associated with a variety of human diseases, including acute myeloid leukemia, myeloproliferative neoplasms, and human immunodeficiency virus/acquired immunodeficiency syndrome (HIV/AIDS)." (PMID 34217312, 2021).
lung adenocarcinoma (3 papers, 2022 to 2025). A carcinoma that arises from the lung and is characterized by the presence of malignant glandular epithelial cells. "However, the expression and possible function of CPSF6 in lung adenocarcinoma (LUAD) still needs to be explored." (PMID 36446361, 2022). "CPSF6-mediated shortening of the XBP1 3’ UTR alleviates cisplatin-induced ER stress and enhances chemoresistance in lung adenocarcinoma." (PMID 40544380, 2025).
acute promyelocytic leukemia (2 papers, 2020 to 2022). An aggressive form of acute myeloid leukemia (AML), characterized by arrest of leukocyte differentiation at the promyelocyte stage, due to a specific chromosomal translocation t(15;17) in myeloid cells. "Another fusion protein harbouring CPSF6 is CPSF6-RARG, which was found in several hematopoietic malignancies, showing morphological and immunophenotypical features of classical hypergranular acute promyelocytic leukemia (APL)." (PMID 32408494, 2020).
colon cancer (2 papers, 2021). "In the colon cancer cells expressing Snail1, expression of CPSF6 and splicing factor proline/glutamine-rich (SFPQ) is higher than that of the control group, suggesting the pro-oncogenic effect of CPSF6." (PMID 34217312, 2021).
Insulin resistance (2 papers, 2023). Increased resistance towards insulin, that is, diminished effectiveness of insulin in reducing blood glucose levels. "Additionally, YTHDC1 has been implicated in the regulation of glucose metabolism and insulin resistance by interacting with serine/arginine splicing factor (Srsf3) and cleavage and polyadenylation specific factor 6 (Cpsf6) to regulate mRNA splicing of in mouse β-cells." (PMID 37628704, 2023).
liver cancer (2 papers, 2022 to 2024). An epithelial or non-epithelial malignant neoplasm that arises from the liver. "As a fusion partner of FGFR1 (fibroblast growth factor receptor 24, CPSF6 is involved in the progression of acute myeloid leukemia 25, HIV-1 infection 26, breast cancer 27, gastric cancer 28 and liver cancer." (PMID 38993554, 2024). "Overall, these findings suggest that CPSF6 enhances the Warburg effect for immune escape and angiogenesis, leading to cancer progression via c-Myc, mediated by the HK, PD-L1, and VEGF networks, with synergistic potential with sorafenib as a molecular target for liver cancer therapy." (PMID 38993554, 2024). "In summary, these findings suggest that CPSF6 enhances the Warburg effect and angiogenesis, leading to cancer progression via c-Myc mediated by the HK, PD-L1, and VEGF networks, with its siRNA synergistic effect with sorafenib as a molecular target in liver cancer therapy." (PMID 38993554, 2024).
lung carcinoma (2 papers, 2022). "The relationship between CPSF6 and lung cancers is still needed to be revealed." (PMID 34986865, 2022). "To clarify the benefits of CPSF6 inhibition in LUAD, we knocked down the expression of the CPSF6 gene in two human LUAD cell lines, A549 and NCI-H1299, by lentivirus-mediated RNA interference (RNAi) and evaluated the alterations in lung cancer proliferation and apoptosis." (PMID 36446361, 2022).
neuroblastoma (2 papers, 2015 to 2024). Neuroblastoma (NB) is the most common solid, extracranial childhood tumor. "We validated the function of CPSF6 in neuroblastoma cells and found that, indeed, loss of CPSF6 led to a dramatic switch from GAC to KGA in BE2C and SK-N-AS cells." (PMID 38488852, 2024).
prostate carcinoma (2 papers, 2024 to 2025). A carcinoma that arises from epithelial cells of the prostate gland. "Consistently, CPSF6 was overexpressed in stages I-VI of HCC and was highly expressed at the mRNA level in various cancer cell lines, including breast, liver, colon, and prostate cancers." (PMID 38993554, 2024).
anemia (1 paper, 2023). A reduction in the number of red blood cells, the amount of hemoglobin, and/or the volume of packed red blood cells. "CPSF6 indirectly modulates glucose homeostasis and insulin secretion, while HBA2, a commonly known marker for anemia and β-thalassaemia, interferes with glycemic markers in T2DM patients." (PMID 37686344, 2023).
iron deficiency (1 paper, 2026). "Functional assays demonstrated that CPSF6 facilitates erythropoiesis, as its depletion impaired heme synthesis and intracellular iron deficiency." (PMID 41805127, 2026).
latent infection (1 paper, 2021). "Based on CPSF6's participation in cellular transcription, here we undertook efforts to ascertain whether CPSF6 plays a significant role in HIV-1 transcription in the context of latent infection." (PMID 34154414, 2021).
lung squamous cell carcinoma (1 paper, 2022). "CPSF6 is significantly higher expressed in tumor tissues than normal tissues in multiple cancer types, especially in both LUAD and lung squamous cell carcinoma (LUSC)." (PMID 36446361, 2022).
oesophageal cancer (1 paper, 2023). "In addition, some studies have shown that the RBP CPSF6 can participate in the pathogenesis of oesophageal cancer by regulating circCPSF6." (PMID 37428781, 2023).
sarcoma (1 paper, 2012). A usually aggressive malignant neoplasm of the soft tissue or bone. "CFIm68 (cleavage factor Im 68 kDa, also known as CPSF6), and Fus (fused in sarcoma) are coincidentally identified as components of the nuclear bodies." (PMID 22476590, 2012).
infection (60 papers, 2010 to 2026). The state of being infected such as from the introduction of a foreign agent such as serum, vaccine, antigenic substance or organism. "(B) The graph shows the percentage of CPSF6 puncta associated with nuclear speckle (NS) or adjacent to NS or isolated from NS at different time post-infection." (PMID 41493399, 2026). "(C) The graph shows the progression of CPSF6 puncta associated with NS during the time post-infection." (PMID 41493399, 2026). "The results were consistent with our IVT-SAPAS data indicating that all tested genes exhibited appreciable 3’ UTR shortening upon VSV-eGFP infection or CPSF6 deficiency, and that ectopic expression of CPSF6 partially prevented this trend." (PMID 38416782, 2024). "HIV-1 with N57A, Q63A/Q67A, K70A, or T107A mutations in CA are reduced in sensitivity to CPSF6-mediated infection blocks and are similarly diminished in binding CPSF616." (PMID 37355754, 2023). "Because N74D HIV-1 and P90A HIV-1 were insensitive to Nup35 depletion, we examined other viruses with CA mutations that influence interaction with CPSF6 or CypA for infection of Nup35 knockdown cells." (PMID 37355754, 2023). "HIV-1 with mutations in CA that prevent interaction with soluble factors such as CPSF6 and CypA, exhibit a differential dependence on Nups during infection, including loss of reliance on both Nup153 and Nup358." (PMID 37355754, 2023). "PF74 has bimodal inhibition kinetics, in which at low concentrations it reduces infection by competing with cofactors Nup153 and CPSF6 while at high concentrations it causes irreversible and catastrophic uncoating that prevents reverse transcription." (PMID 31851928, 2019). "There are as yet no examples where perturbing the recruitment of these nuclear entry cofactors (through depletion or CA mutation) reduces infection of viruses that cannot engage CPSF6." (PMID 25356722, 2014). "The antiviral action of CPSF6 is physiologically relevant to HIV-1 replication in vivo, because we find that CPSF6 inhibits infection of early CTL escape variants in HLA-B27+ individuals." (PMID 24415937, 2014). "Taken together, we demonstrate that endogenous CPSF6 hampers infection of naturally occurring HIV-1 CA variants, possibly through binding to incoming viral capsids together with CypA." (PMID 24415937, 2014). "Treatment of TNPO3 knock-down cells with 2 μM PF74 during infection strongly reduced the level of CPSF6 association with RTC/PIC to 18% (74 RTC/PIC analyzed)." (PMID 25517934, 2014). "For this purpose, we challenged Cf2Th cells stably expressing the different CPSF6 variants by increasing amounts of HIV-1 expressing GFP as a reporter for infection." (PMID 23622145, 2013). "This lack of correspondence between magnitude of structural defect and loss of infection supports the conclusion that CPSF6 defines an interface in which residues have a role in mediating protein interaction necessary for optimal infection." (PMID 22956906, 2012). "Notably, HIV-1 CA is known to regulate reverse transcription and post-reverse transcription steps of infection, and the CPSF6–CA interaction is implicated in nuclear entry and post-nuclear entry steps of infection (75, 78, 81, 83, 107, –, 109)." (PMID 40202316, 2025). "Additionally, it is known that abolishing the CA/CPSF6 interaction alters the spatiotemporal staging of infection, such that the viral core remains associated with the nuclear envelope." (PMID 39823525, 2025). "If transcriptional rewiring triggered by CPSF6 recruitment to capsid cores enhances CD4+ T cell permissivity to infection, we would expect that mutations that prevent CPSF6 binding would decrease infectivity and that knock-out of CPSF6 would help rescue infection of those viruses." (PMID 39678349, 2024).